CAPN15 (calpain 15)
Description:
Calcium-dependent cysteine protease that functions as a non-proteasomal, ubiquitin-directed protease regulating cell adhesion through cleavage of E-cadherin/CDH1. Binds to ubiquitinated proteins via its N-terminal, preferentially recognizing longer polyubiquitin chains including both 'Lys-48- and 'Lys-63'-linked chains. Recognizes the ubiquitinated E-cadherin-catenin complex and cleaves E-cadherin in a calcium- and ubiquitination-dependent manner resulting in lysosomal degradation of the resultant fragment. Plays a critical role in eye, brain and cerebellar development (By similarity). In the developing brain, may regulate transcription factor abundance including PAX2 and PAX5 levels. Additional putative substrates include P-cadherin/CDH3, DCX and TUBB3 (By similarity).
Synonyms: SOLH; OGIN
Tractability: PROTAC: ubiquitination databases record sites on it.
Gene: Protein-coding gene on chromosome 16 (527,712 to 554,636, forward strand). Ensembl gene ENSG00000103326.
Subcellular location (Human Protein Atlas): Nucleoplasm
Pathways (Reactome):
Extracellular matrix organization: Degradation of the extracellular matrix
Gene Ontology:
Molecular function: cysteine-type peptidase activity; protein binding; calcium-dependent cysteine-type endopeptidase activity
Biological process: cell adhesion; brain development; proteolysis
Cellular component: cytoplasm
Genetic constraint (gnomAD): Loss-of-function variants: 53 observed, 68.39 expected, observed/expected ratio (o/e) 0.77, 90% interval 0.62 to 0.97. The synonymous counts are far from expectation, so gnomAD's model fits this gene poorly and the ratio says little. Missense variants: 1,592 observed, 1,378.5 expected, observed/expected ratio (o/e) 1.15, 90% interval 1.11 to 1.2. Synonymous variants: 922 observed, 635.69 expected, observed/expected ratio (o/e) 1.45, 90% interval 1.37 to 1.53.
Homologues: Orthologues: macaque CAPN15 (97% identical), chimpanzee CAPN15 (94% identical), mouse Capn15 (88% identical), rat Capn15 (88% identical), guinea pig CAPN15 (88% identical), dog CAPN15 (86% identical), rabbit CAPN15 (83% identical), pig CAPN15 (82% identical), zebrafish capn15 (68% identical), tropical clawed frog capn15 (65% identical), Drosophila melanogaster sol (43% identical), Caenorhabditis elegans clp-9 (23% identical), and 1 more. Paralogues in human: CAPN1 (15% identical), CAPN8 (15% identical), ADGB (14% identical), CAPN2 (14% identical), CAPN3 (14% identical), CAPN9 (14% identical), CAPN12 (14% identical), CAPN11 (13% identical), CAPN14 (12% identical), CAPN5 (11% identical), CAPN7 (11% identical), CAPN10 (11% identical), and 8 more.
Diseases named in the same sentence as CAPN15 in open-access papers:
CAPN15 is named in the same sentence as 13 diseases in open-access papers, as found by Europe PMC text mining. Sharing a sentence is not in itself a finding about the gene and the disease. The quoted sentences say what the papers report.
developmental delay (2 papers, 2024 to 2025). "Human individuals with biallelic variants in CAPN15 have developmental delay, neurodevelopmental disorders, as well as congenital malformations, including eye anomalies." (PMID 40238785, 2025). "Two missense variants in the CAPN15 gene were assessed in a patient displaying irido-choroidal coloboma associated with a mild developmental delay (A106)." (PMID 38459225, 2024).
oculogastrointestinal-neurodevelopmental syndrome (2 papers, 2022 to 2024). "In three of these cases, the diagnosis was made via rapid genome sequencing with trio analysis: CAPN15-related oculogastrointestinal neurodevelopmental syndrome, TTN-related disorder, and STAC3-related myopathy." (PMID 36422100, 2022).
cataract (1 paper, 2025). Partial or complete opacity of the crystalline lens of one or both eyes that decreases visual acuity and eventually results in blindness. "Similarly, Capn15 KO mice exhibit growth retardation with eye hypoplasia, cataracts, and smaller brains, suggesting that the loss of CAPN15 function contributes to the pathogenesis of OGIN." (PMID 41380969, 2025).
cryptorchidism (1 paper, 2022). The failure of one or both testes of a male fetus to descend from the abdomen into the scrotum during the late part of pregnancy. "Furthermore, some genes identified in the BTA 25 may have a deleterious role on male andrological parameters, such as the Calpain-15 (CAPN15), which has a causal variant affecting cryptorchidism susceptibility in rats." (PMID 35692843, 2022).
Johanson-Blizzard syndrome (1 paper, 2025). A multiple congenital anomaly characterized by exocrine pancreatic insufficiency, hypoplasia/aplasia of the nasal alae, hypodontia, sensorineural hearing loss, growth retardation, anal and urogenital malformations, and variable intellectual disability. "Capn15 loss is the cause of a small subset of patients with Johanson-Blizzard syndrome." (PMID 40238785, 2025).
tumor (2 papers, 2019 to 2023). "Additional genes that had similar DNA and RNA frequency as DUSP5 and EI24 but no previous research on their potential role as a tumor suppressor were UBXN11, CAPN15, C6orf62, GPRIN1, KIAA2018, PCDHGA10, and PCGF1." (PMID 31484939, 2019).
infection (1 paper, 2018). The state of being infected such as from the introduction of a foreign agent such as serum, vaccine, antigenic substance or organism. "Infection of HeLa cells with recombinant THOV wild type (rTHOV-wt) as well as with the virus bearing TE mutation in ML (rTHOV-TE), which is still capable to bind TFIIB but cannot bind CAPN15, induced only minimal amounts of IFN-α/β." (PMID 29709033, 2018).
neurodevelopmental disorder (1 paper, 2025). A behavioral and cognitive disorder with onset during the developmental period that involves impaired or aberrant development of intellectual, motor, or social functions. "Humans carrying homozygous variants of CAPN15 also exhibited a variety of neurodevelopmental disorders." (PMID 40238785, 2025). "We focused on P2 brains as Capn15 is widely expressed at this time, but levels of Capn15 are higher in embryonic brain and many proteins whose loss is responsible for neurodevelopmental disorders act earlier during neuronal differentiation that peaks in embryonic brains." (PMID 40238785, 2025).
CAPN15 also shares sentences with these, for which no sentence is quoted: brain disease (1 paper); brain malformations (1); cancer (1); myopathy (1); osteosarcoma (1).